E2F4 (E2F transcription factor 4)
Diseases named in the same sentence as E2F4 in open-access papers (continued):
Sharing a sentence is not in itself a finding about the gene and the disease.
tumor (continued). "Colony formation and proliferation assays confirmed that E2F4 plays a consistent role in promoting tumor growth in PCa." (PMID 40560737, 2025). "Nuclear receptors RORa, NR2F6 and HNF4G are uncovered as candidate transcriptional drivers of these cells whilst closure of binding sites for E2F2 and E2F4 indicate post-treated tumour having low proliferative capacity." (PMID 39341888, 2024). "Multivariate regression analysis confirmed these factors as independent risk factors for GC progression (P < 0.05): tumor size, lymph nodes metastasis, distant metastases, TNM stage, E2F4 expression, and DSCC1 expression." (PMID 39309429, 2024). "E2F4 is part of the E2F family of transcription factors, which play a key role in the control of cell cycle and act as tumor suppressor proteins." (PMID 39161957, 2024). "Western blot analysis confirmed that E2F4 knockdown effectively reduced its expression in the tumor tissues." (PMID 39309429, 2024). "To elucidate the functions of E2F4 in vivo, we established subcutaneous tumor models in nude mice by injecting NCI-N87 cells, following previously reported methods." (PMID 39309429, 2024). "E2F1, E2F3, and E2F4 are all transcription factor E2F family members, which are critical in controlling tumor-suppressor protein production and the cell cycle and are also targeted by small-DNA tumor virus transformation proteins." (PMID 37504265, 2023). "In HCC, the E2F4 expression level was positively correlated with tumor size, and E2F4 overexpression significantly enhances HCC cell proliferation, migration, and invasion." (PMID 37504265, 2023). "Current research indicates that the E2F family, including E2F1 and E2F4, regulates cell cycle, tumorigenesis and progression of multiple tumours." (PMID 37779874, 2023). "At the same time, USP2 stabilizes the E2F4 protein through deubiquitination, reducing its transactivation in tumor cells and thereby inhibiting its protective autophagy." (PMID 36611139, 2023). "Current studies demonstrate that the E2F family comprising E2F1 and E2F4 regulates the cell cycle tumour development and progression." (PMID 37779874, 2023). "Meanwhile, MNX1 and E2F4 effects on cell migration, invasion and tumour growth were examined through in vivo and in vitro assays." (PMID 37779874, 2023). "Next, we isolated tumor tissues (TT) and adjacent non-tumor tissues (ANTT) from 25 patients with HBV-associated HCC and compared their E2F4, Id1, and HBV expression." (PMID 34975318, 2022). "We believe E2F4 promoted tumor growth by facilitating the proliferation, and inhibiting the apoptosis, of cancer cells and thus enhanced the malignancy of tumor cells." (PMID 35840663, 2022). "Immune cell infiltration in tumors is an integral part of TME, and the estimate and ssGSEA algorithms were used to assess the proportion of each component of the TME and the correlation between tumor immune cell infiltration and E2F4." (PMID 36567912, 2022). "Immunohistochemical staining showed that E2F4 was mainly located in the cell nuclei of tumor tissues." (PMID 35840663, 2022). "E2F4 is a novel tumor marker and well-established transcription factor that has been associated with HCC prognosis." (PMID 36211823, 2022). "Third, we explored the relationship between E2F4 expression and tumor infiltration into immune cells." (PMID 35840663, 2022). "E2F4 expression is abnormally increased in the malignant tumor tissues of gastric, breast, and colorectal cancers." (PMID 35840663, 2022). "Based on the GEO dataset “GSE13601”, the E2F4 expression level in tumor tissues was significantly higher than that in normal tissues (P < 0.05)." (PMID 35840663, 2022). "To validate the results, we analyzed E2F4 expression in the TCGA database: the E2F4 expression level was significantly greater in HNSCC tumor tissues than in normal mucosal tissues (P < 0.05)." (PMID 35840663, 2022).
tumor (continued). "Analysis of the correlation between E2F4 expression and clinicopathological features revealed that most patients with tumor sizes > 5 cm (16/24) exhibited upregulated E2F4 expression." (PMID 34335934, 2021). "On the other hand, we observed an increased expression of CDK4 and E2F4 in tumor cells isolated from ZF-cluster, genes regulating cell cycle progression." (PMID 34502201, 2021). "Based on these results, the relationship between E2F4 and hub genes was a novel reason for tumor progression." (PMID 33613768, 2021). "Another study demonstrated that E2F4 played an essential role in the drug-sensitivity and tumor progression of epithelial ovarian cancer." (PMID 33613768, 2021). "In regards to the tumor grade, significant differences in E2F4 transcription were found between both grade 1 and grade 2 when compared to grade 3 (all p < 0.05)." (PMID 33613768, 2021). "A growing body of evidence also shows that E2F4 is remarkably correlated with tumor immune cell infiltration." (PMID 33613768, 2021). "Taken together, these results indicate that E2F4 functions as a tumour suppressor in AML via inhibition of the MAPK signalling pathway by binding to EZH2." (PMID 31943751, 2020). "To verify the effect of the transcription factor E2F4 on tumour formation in vivo, we first established the stable cell line NB4, with E2F4 shRNA knockdown or with control shRNA as a negative control." (PMID 31943751, 2020). "The protein expression of N‐cadherin, vimentin, MMP‐2 and MMP‐9 was profoundly elevated in tumours of nude mice injected with oe‐HAND2‐AS1 + sh‐E2F4 and oe‐HAND2‐AS1 + oe‐C16orf74 (P < .05)." (PMID 32314545, 2020). "Taken together, our results expanded our knowledge of the regulatory network between E2Fs and EZH2 in AML and confirmed that E2F4 functions as a tumour suppressor in AML via inhibition of the MAPK signalling pathway by binding to EZH2." (PMID 31943751, 2020). "The photographs and tumour volumes measured showed that cell growth was much slower in E2F4‐silenced cell tumours than in control cell tumours." (PMID 31943751, 2020). "In our report, we demonstrated that the expression of E2F4 was lower in LC tissues than in normal tissues, but this expression was markedly correlated with tumor stage in patients with LC." (PMID 29754146, 2018). "When stratifying patients into groups based on ER status, tumor stage, and molecular subtype, a high E2F4 iRAS continued to be indicative of improved pCR rate." (PMID 28464832, 2017). "A follow-up study to our work revealed that the E2F4 signature is also predictive of neoadjuvant anthracycline-based chemotherapy response, even after adjusting for tumor grade." (PMID 28464832, 2017). "Patients exhibiting high E2F4 scores were more likely to achieve pCR than patients with lower scores, further validating that the cellular proliferation rate in a patient’s tumor is a good biomarker for predicting neoadjuvant response." (PMID 28464832, 2017). "Patients with high E2F4 activity had significantly worse survival than patients with low activity, a trend consistent with other markers of tumor proliferation rate." (PMID 28464832, 2017). "and Nottingham, shows E2F4 to have a higher hazard ratio, suggesting it is a stronger predictor of tumor prognosis than these two clinicopathological-derived prognostic indices." (PMID 25440089, 2014). "After controlling for many clinical variables including patient age, tumor size, grade, ER status and LN status, the E2F4 iRAS is still highly significant in predicting patient RFS times (P = 6e-6) in a Cox survival regression model." (PMID 25440089, 2014).
tumor (continued). "E2F1 and E2F4 are also identified as TFs with higher activities in tumor epithelium samples, suggesting higher proliferative rate of malignant epithelium breast cells." (PMID 23885756, 2013). "A comparison of E2f4+/+, E2f4+/− and E2f4−/− mice revealed that E2f4−/− mice remained tumor-free for significantly longer than siblings (p<0.0001) with a median tumor-free span of 375 days past birth." (PMID 19749980, 2009). "In contrast, the tumor types from the E2f4−/− mice were heterogeneous with a distribution across both broad categories of the wild type tumors." (PMID 19749980, 2009). "In summary, along with the general delay in tumor onset there was also a difference in the predominant site of lymphomagenesis and gross morphological appearance of tumors in the E2f4−/− Eμ-myc mice." (PMID 19749980, 2009). "Moreover, transcription factor activity analysis revealed elevated activity of several transcription factors, such as ARID2, E2F1, E2F4, NFYB, and MYC, in the RRhighepi group, all of which are closely associated with cell proliferation and tumor progression." (PMID 41424847, 2026). "Since MTDH has been reported to inhibit tumor antigen presentation, we speculated that E2F4-induced MTDH expression contributed to the suppression of antigen presentation." (PMID 41249116, 2025). "A well‐known regulator of the cell cycle and proliferation, the enrichment of E2F4 suggests that the key genes may be connected to cell cycle control, consistent with aggressive tumor behavior or high MYCN activity." (PMID 40600620, 2025). "To investigate whether E2F4 is also involved in FAM114A1-mediated tumor immune evasion, we extensively explored the role of E2F4 in this context." (PMID 41249116, 2025). "Further studies will be needed to clarify the distinct contributions of E2F4 and p130 to determine this alternative repression axis, which could reveal actionable nodes to reinforce tumor suppressive programs in RB-compromised settings." (PMID 41155196, 2025). "In vivo investigations have shown that E2F4 promotes tumor development and metastasis in nude mice." (PMID 39768811, 2024). "In vivo studies further demonstrated that E2F4 enhances tumor growth and metastasis in nude mice." (PMID 39309429, 2024). "In vivo experiments further confirmed that E2F4 promotes tumor growth and metastasis in nude mice." (PMID 39309429, 2024). "In this core signaling pathway, the transduction signaling protein FLII plays a role in regulating cytoskeletal rearrangement involved in cell division and cell metastasis; E2F4 plays an important role in controlling the cell cycle and inhibiting tumor proteins." (PMID 35743172, 2022). "E2F4 plays an important role in tumor progression and may be a critical biological prognostic factor for HNSCC." (PMID 35840663, 2022). "The E2F4 expression was elevated in OSCC tumor tissue compared with paracancerous tissues." (PMID 36567912, 2022). "Therefore, we aimed to expand our current knowledge regarding the E2F4 gene in the regulation of the immune response, taking into consideration tumor purity and immunity." (PMID 35840663, 2022). "These molecular activities are consistent with tumor carcinogenesis, and E2F4 could participate in tumor progression via the regulation of these pathways." (PMID 33613768, 2021). "Therefore, we aimed to expand our current knowledge regarding the E2F4 gene in immune response regulation, taking into consideration the tumor purity and tumor immunity." (PMID 33613768, 2021). "E2F4 expression positively correlated with tumor size in patients with HCC." (PMID 34335934, 2021). "This suggests that the expression of E2F4 is positively correlated with tumor size." (PMID 34335934, 2021).
tumor (continued). "We showed that E2F4 inhibition significantly hampered tumor growth in vivo." (PMID 32641768, 2020). "We found that tumor emergence was accelerated by E2F2 loss and delayed by E2F4 loss." (PMID 19749980, 2009). "An alteration in the apoptotic potential of Myc could account for the differences in Myc-initiated tumor onset among wild type, E2f2-null and E2f4-null animals." (PMID 19749980, 2009). "Finally, we tested whether E2F4 knock-down would translate into increased tumor sensitivity to irinotecan." (PMID 39896677, 2025). "E2F4 plays an important role in the suppression of proliferation-associated genes and recent evidences report that E2F4 may play an oncogenic rather than a tumor suppressor role in cancer cells." (PMID 29448954, 2018). "However, E2F4 can directly repress apoptotic genes, and therefore E2F4 might also promote tumor growth by protecting cancer cells more efficiently against cell death." (PMID 27753528, 2016). "Hence, our findings suggest that dysregulated E2F4 nuclear localization may represent one of the instigating events leading to hyperproliferation and hence of tumor initiation and promotion in the colon and rectum." (PMID 23919615, 2013). "In line with this notion, our results indicate that tumor cells utilize both the PI3K/AKT pathway and the E2F4-driven MTDH pathway to escape immunosurveillance." (PMID 41249116, 2025). "Analysis of TCGA-LIHC database showed that E2F4, E2F5, and E2F6 were upregulated in tumor tissues of HCC compared to normal tissues." (PMID 38166853, 2024). "Prominent discoveries revealed heightened regulon activities of the E2F family (E2F1, E2F4 and E2F2), which are crucial in promoting tumour growth and migration." (PMID 39187937, 2024). "Univariate regression analysis identified several factors affecting OS (P < 0.05): tumor size, lymph nodes metastasis, distant metastases, TNM stage (stages I and II vs. stages III and IV), E2F4 expression (low vs. high), and DSCC1 expression (low vs. high)." (PMID 39309429, 2024). "Among the downregulated DEGs, the shared transcription factors include E2F4/DP1, E2F1/DP2, E2F4/DP2, and E2F1/DP1, which have been identified as important contributors to tumor progression in various cancer types." (PMID 38057925, 2023). "Thus, we suggest that E2F4 may have a potential influence on tumor immunology." (PMID 35840663, 2022). "Among them, GATA1, RARA and LMO2 were lowly expressed, while E2F4 and CTBP2 were highly expressed in tumor parts." (PMID 35743687, 2022). "We also analyzed the correlation of E2F4 expression with the immune-infiltration level of HNSCC in an attempt to find out the interaction between E2F4 and tumor infiltration into immune cells in HNSCC." (PMID 35840663, 2022). "Genes significantly associated with the outcomes were enriched for early estrogen response pathway, DNA repair pathways as well as targets of transcription factors such as E2F4, MYC, and ETS1 that have recognized roles in tumor characteristics and survival." (PMID 36584096, 2022). "Consistently, tumour size and weight in mice harbouring HAND2‐AS1 overexpression and E2F4 silencing or C16orf74 overexpression were markedly increased relative to the control mice (P < .05)." (PMID 32314545, 2020). "Patients diagnosed with more advanced tumor grades at metastases showed CTCs with high expression levels of KRT5 and low expression of E2F4 (p = 0.024)." (PMID 31817194, 2019). "Our results suggest that transcription factors E2F4, AR and ETS1 are potential key regulators in tumour progression." (PMID 24523864, 2014).
tumor (continued). "The constitutive expression of E2F4 and CDK6 genes was increased in our study cohort of RB tumor tissues analyzed here." (PMID 23077401, 2012). "WPMY-1 cells, while sharing some TFs, showed higher activity of TFs associated with cell cycle regulation and proliferation, such as E2F family members (E2F1, E2F4, E2F8) and JUN, highlighting key regulatory differences between tumor-derived CAFs and benign stromal fibroblasts." (PMID 41198614, 2025). "First, we found that E2F4 formed puncta in tumor cells and that the proportion of cells with puncta significantly increased upon FAM114A1-KD, suggesting that FAM114A1 inhibited E2F4 condensate formation." (PMID 41249116, 2025). "In our experimental system, E2F4 knock-down did not translate into a reduction in the frequency of organoid-initiating cells (in vitro) or the frequency of tumor-initiating cells (in vivo) as evaluated by an extreme limiting dilution assay (ELDA)." (PMID 39896677, 2025). "In addition, reports have shown that GAS5 interacts with some proteins, such as E2F1, E2F4, YBX1, EZH2, and YAP, which inhibit tumor progression." (PMID 38782769, 2024). "Previously, it was reported that miR17-5p could repress RBL2, also named P130, to release activating transcription factor E2F4 or CTNNB1, which promoted tumor progression by inducing activation of multiple targeted genes like CCND1 and CCNE1 etc.." (PMID 37506248, 2023). "Together, these data indicate that, as in the in vitro experiments, E2F4 may affect the proliferation and differentiation of AML tumours in vivo." (PMID 31943751, 2020). "Western blotting showed that E2F4 knockdown promoted the expression of CD11b and CD14 and inhibited the expression of cyclin D1, cyclin A2, P‐Rb and CDK4 compared with the expression in control tumours." (PMID 31943751, 2020). "Our present data revealed that E2F4 exerts relevant roles in epidermis in absence of pRb, including tumor suppressive functions." (PMID 27708231, 2016). "We find that in normal samples and superficial tumor samples, the activity for the modules of the E2F1, E2F2 and E2F3 target genes is lower than in invasive tumors, as opposed to the target genes of the inhibitory transcription factors E2F4 and E2F6." (PMID 26925094, 2016). "Finally from these disease modules we identify their upstream transcription factors E2F4, AR and ETS1 as potential key regulators in tumour progression." (PMID 24523864, 2014). "Distinct tumor types emerged with their relative proportions influenced by E2F2 and E2F4 status." (PMID 19749980, 2009). "We also find that distinct types of tumors emerge from the Eμ-myc mice, distinguished by different patterns of gene expression, and that the relative proportions of these tumor types are affected by the absence of either E2F2 or E2F4." (PMID 19749980, 2009). "Two genes involved in telomere maintenance, TERF2 and TERF2IP were among those ruled out as tumor suppressors on 16q, as was E2F4." (PMID 16620391, 2006). "In this study, we identified E2F4, a key mechanistic component of the DREAM transcriptional repression complex, as an important regulator of CRC sensitivity to irinotecan (CPT-11), a derivative of camptothecin (CPT) and a key anti-tumor drug used as standard-of-care for metastatic CRC." (PMID 39896677, 2025). "Tumor cells with FAM114A1-KD presented significantly lower E2F4 protein levels in nuclear fractions, suggesting that FAM114A1 may facilitate E2F4 nuclear translocation." (PMID 41249116, 2025). "Targeting PI3K/AKT may not be sufficient, as tumor cells can exploit E2F4/MTDH to develop resistance." (PMID 41249116, 2025).